BCL6 (BCL6 transcription repressor)
Diseases named in the same sentence as BCL6 in open-access papers (continued):
Sharing a sentence is not in itself a finding about the gene and the disease.
diffuse large B-cell lymphoma (continued). "FBXO11 gene silencing led to the development of diffuse large B-cell lymphoma (DLBCL) by targeting the degradation of Bcl-6, while FBXO11 inactivation resulted in abnormal germinal-centre formation." (PMID 31159774, 2019). "Researchers have been using RNA interference or soluble inhibitor to silence BCL6 to treat cancers in vitro or in an animal model, especially diffuse large B-cell lymphomas with aberrant BCL6 expression." (PMID 31754389, 2019). "This study investigates the protein expression of C-MYC, BCL-2, and BCL-6 in diffuse large B-cell lymphoma (DLBCL) and their relationship with genetic abnormalities." (PMID 30666200, 2018). "Bcl-6, a proto-oncogene overexpressed in diffuse large B-cell lymphoma (DLBCL), is targeted by FBXO11 for polyubiquitination and degradation." (PMID 30359271, 2018). "BCL6 is found to be highly expressed in follicular lymphoma and Burkitt’s lymphoma, and its locus is frequently translocated and hypermutated in diffuse large B cell lymphoma (DLBCL) and nodular lymphocyte predominant Hodgkin lymphoma." (PMID 29728695, 2018). "The oncogenic potential of the transcriptional repressor Bcl-6 (B-cell lymphoma 6) was originally discovered in non-Hodgkin patients and the soluble Bcl-6 inhibitor 79-6 was developed to treat diffuse large B-cell lymphomas with aberrant Bcl-6 expression." (PMID 27880939, 2017). "To evaluate UV-ChIP-seq we investigated genome-wide DNA binding of the sequence-specific transcription factor B-cell lymphoma 6 (BCL6) in human diffuse large B-cell lymphoma (DLBCL) cells." (PMID 29101361, 2017). "When a second xenograft model based on the Bcl-6 independent diffuse large B-cell lymphoma (DLBCL) Toledo cell line was tested, application of the 79-6 inhibitor comparably did not enhance tumor growth (data not shown)." (PMID 27880939, 2017). "With regard to BCL6, this prevents apoptosis and has been reported to predict survival in patients with diffuse large-B-cell lymphoma." (PMID 28881619, 2017). "The BCL6 oncogene plays a crucial role in sustaining diffuse large B-cell lymphomas (DLBCL) through transcriptional repression of key checkpoint genes." (PMID 26657288, 2016). "Studies of investigational drug RI-BPI, which inhibits BCL6 by abrogating its interaction with BCOR, show efficacy against diffuse large B-cell lymphomas (DLBCL) with BCL6, representing yet another potential targeted therapy for specific qWT patients." (PMID 27974047, 2016). "In this study, we assessed rearrangements and expression of MYC, BCL2 and BCL6 in 898 patients with de novo diffuse large B-cell lymphoma treated with standard chemotherapy (cyclophosphamide, doxorubicin, vincristine, and prednisone plus rituximab)." (PMID 26573234, 2016). "Although overexpression of Bcl-6 was frequent in diffuse large B cell lymphoma, its involvement in other cancer types was controversial." (PMID 27237631, 2016). "The BCL6 (B-Cell Lymphoma 6) gene is a proto-oncogene that is often expressed in diffuse large B-cell lymphomas (DLBCLs)." (PMID 27815824, 2016). "While the roles of BCL6 in preventing terminal differentiation of B cells in the germinal center and promoting diffuse large B cell lymphoma are well known, little is currently known about the roles of BCL6 in solid tissue." (PMID 26697522, 2015). "Many of these pairs (such as miR-15 b/BCL2 in apoptosis or BART-6/BCL6 in diffuse large B-cell lymphomas) were experimentally discovered and/or computationally predicted." (PMID 25858286, 2015). "As a result, Bcl6 can act as an oncogene in germinal center-derived lymphomas such as Diffuse Large B-cell Lymphoma." (PMID 24892698, 2014). "Recently, FBXO 11 has been shown to target the pro-oncogene product BCL6 for degradation and to be inactivated in diffuse large B cell lymphomas." (PMID 24968003, 2014). "BCL6 is a transcriptional repressor that is over-expressed due to chromosomal translocations, or other abnormalities, in ∼40% of diffuse large B-cell lymphoma." (PMID 24595451, 2014).
diffuse large B-cell lymphoma (continued). "Bcl6 is a known proto-oncogene that is frequently translocated in diffuse large B cell lymphoma (DLBCL)." (PMID 24252550, 2013). "Hsp90 inhibitors selectively kill diffuse large B cell lymphomas (DLBCLs) that depend on the BCL-6 transcriptional repressor." (PMID 24280675, 2012). "The authors found that in the course of transformation from the rather indolent follicular lymphoma into the more aggressive diffuse large B-cell lymphoma, LAZ3/BCL6 translocations with RHOH were widespread." (PMID 18823547, 2008). "B-cell lymphoma 6 (BCL6) is an attractive drug target for diffuse large B-cell lymphoma (DLBCL)." (PMID 42070207, 2026). "The findings of the study demonstrated that DC-Exo encapsulating BCL6 siRNA effectively inhibited the proliferation of diffuse large B-cell lymphoma (DLBCL) in vitro and significantly suppressed tumor growth in murine models without exhibiting notable toxicity." (PMID 40142991, 2025). "In our previous studies, we reported a series of BCL6 inhibitors with pyrimidinamine scaffold with good inhibitory activities against diffuse large B-cell lymphoma both in vitro and in vivo, but their BCL6 inhibitory activities remained at the micromolar level." (PMID 40821118, 2025). "BCL6 and MEF2B (member of the MEF cluster) are both crucial regulators of B-cell development, and changes in their COF interactions have been implicated in diffuse large B-cell lymphoma (DLBCL)." (PMID 39166482, 2024). "However, this signaling pathway is obstructed in a specific subgroup of diffuse large B-cell lymphomas (DLBCLs) due to genetic changes or modifications in the BCL6 gene." (PMID 38864622, 2024). "However, this study was conducted under the context of diffuse large B-cell lymphomas, highlighting the need for a greater understanding of the co-expression of BCL6 and CD10 in MCL." (PMID 37373354, 2023). "Additionally, CRISPR/Cas9 was used to knock out the BCL–6 gene in Diffuse Large B-cell Lymphoma (DLBCL), which resulted in stagnation of cell cycle (G1) in tumor cells, bringing hope for curing this disease." (PMID 36193328, 2022). "At present, research on BCL6 mainly focuses on the structure formation of the B-cell germinal center, because BCL6 is also closely related to diffuse large B-cell lymphoma (germinal center type), and is thought to be a target for the treatment of cancer and autoimmune diseases." (PMID 33541426, 2021). "Indeed, BCL6 bound to both distinct and common sets of functionally related gene in normal GC cells versus diffuse large B-cell lymphomas-derived cells." (PMID 31903146, 2020). "Moreover, GSK-J4 treatment sensitized diffuse large B-cell lymphoma to chemotherapy drugs through the downregulation of B-cell receptor signaling and Bcl-6." (PMID 31065671, 2020). "Additionally, miR-10a was found to inhibit cell proliferation by targeting BCL6 in diffuse large B-cell lymphoma." (PMID 31455210, 2019). "MiR-144 was shown to target BCL6 in diffuse large B-cell lymphoma." (PMID 29731996, 2018). "Though BCL6 could suppress BCL2 in diffuse large B-cell lymphoma, we found that the expression of these two proteins exhibits positive correlation in glioblastoma cells." (PMID 30420967, 2018). "Other examples of translocation between IGH and other oncogenes are BCL2 in FL, BCL6 in diffuse large B cell lymphoma (DLBCL) and CCND1 (Cyclin D1), CCND3 (Cyclin D3), FGFR3/MMSET (Fibroblast growth factor receptor 3/multiple myeloma SET domain), and MAF (c-maf) in multiple myeloma (MM)." (PMID 28867784, 2017). "The approach to inhibit oncogenic protein-protein interactions by particular peptides or small molecules has been realized for BCL6 in diffuse large B-cell lymphoma and may be applicable to SIX1 as well, disturbing its oncogenic transcriptional activity." (PMID 26473286, 2015).
diffuse large B-cell lymphoma (continued). "BCL6, a zinc finger transcription factor, regulates the transcription of a variety of genes involved in B cell development, differentiation, and activation and is overexpressed in the majority of patients with aggressive diffuse large B cell lymphoma." (PMID 24968003, 2014). "The expression of BCL6 may strongly predict survival in patients with diffuse large B-cell lymphoma." (PMID 20856936, 2010). "Interestingly, BCL6 expression in diffuse large B cell lymphomas has been shown to strongly correlate with better survival in patients with this disease." (PMID 19226467, 2009). "We have recently shown that heterozygous transgenic iMycEμ mice that carry one mutated and one normal Igh locus are prone to mature B cell and plasma cell neoplasms including IgM+ lymphoblastic B-cell lymphoma (LBL), Bcl-6+ diffuse large B cell lymphoma, and Ig-secreting CD138+ plasmacytoma (PCT)." (PMID 16759389, 2006). "In a cellular model of diffuse large B-cell lymphoma (DLBCL), the inhibition of HDAC3 rescues the aberrant epigenetic programming associated with CREBBP mutations, enhancing BCL6-mediated antigen presentation and the release of IFN-γ." (PMID 40006729, 2025). "In diffuse large B-cell lymphoma, small-molecule inhibition of STAT3, a transcriptional target of BCL6, has shown promise in chemotherapy-refractory activated B-cell-like DLBCL." (PMID 40805145, 2025). "In a recent study to suppress diffuse large B-cell lymphoma (DLBCL) progression, researchers engineered iRGD-modified exosomes to deliver B-cell lymphoma 6 (BCL6) siRNA to knock down BCL6." (PMID 39355533, 2024). "Here, we report that mice with endothelial cell-specific deletion of Fbw7 spontaneously developed diffuse large B-cell lymphoma (DLBCL) following Bcl6 accumulation." (PMID 38485719, 2024). "Histopathological examination diagnosed a triple-expressor gastric Diffuse Large B-Cell Lymphoma (DLBCL) [Bcl-2 focal (60%), Bcl-6 focal (40%), C-Myc (10%), CD10 focal (70%)]." (PMID 38997875, 2024). "Immature DC-derived exosomes that have been loaded with B-cell lymphoma 6 (BCL6) siRNA via electroporation suppress the proliferation of diffuse large B-cell lymphoma (DLBCL)." (PMID 37242707, 2023). "The MTA3 subunit of the NuRD complex interacts with BCL-6, an oncogene that has transformative potential in diffuse large B-cell lymphoma (DLBCL)." (PMID 37046781, 2023). "Likewise, in B-cell malignancies, proto-oncogenes are often translocated to the locus of the immunoglobulin heavy chain (IGH), such as MYC in Burkitt lymphoma (IGH/MYC), CCND1 in mantle cell lymphoma, BCL-6 in diffuse large B-cell lymphoma (DLBCL) and BCL-2 in follicular lymphoma." (PMID 35563017, 2022). "In Diffuse Large B-cell Lymphoma (DLBCL), however, the aberrant persistence of BCL6 expression (e.g., due to chromosome translocations and/or point mutations) plays a critical role in lymphomagenesis." (PMID 36329085, 2022). "The B-cell lymphoma 6 (BCL6) oncogene is required for the survival of diffuse large B-cell lymphoma (DLBCL), which is incurable using conventional chemotherapy." (PMID 35883106, 2022). "Background/Aim: Peli1 is an E3 ubiquitin ligase involving lymphomagenesis by lysine 63 ubiquitination-mediated stabilization of Bcl-6 with in diffuse large B-cell lymphoma (DLBCL)." (PMID 36606193, 2022). "However, in follicular lymphoma (FL) and diffuse large B cell lymphoma (DLBCL), CREBBP mutations disable its acetylation and result in unopposed deacetylation by the BCL6-SMRT-HDAC3 complex at enhancers of B cell signal transduction and immune response genes, thus promoting lymphomagenesis." (PMID 31910827, 2020).
diffuse large B-cell lymphoma (continued). "JMJD3 was found to promote phosphorylation of proteins mediating BCR signaling and up-regulate proto oncogene B-cell lymphoma/leukemia 6 (Bcl6) levels to facilitate diffuse large B-cell lymphoma (DLBCL) progression." (PMID 31701394, 2019). "Importantly, meta-analysis of microarray data from diffuse large B-cell lymphoma patients found that miR-155 expression correlated negatively with Bcl6 and Hdac4 expression, strongly supporting the role of the miR-155/Bcl6/Hdac4 pathway in the pathogenesis of human leukemias." (PMID 29354135, 2017). "Interestingly, PTPROt may itself be a target for repression by BCL6 as the latter modulates tonic BCR signaling in diffuse large B-cell lymphoma." (PMID 29371952, 2017). "Recent studies have showed, both mRNA and protein expression of LITAF are significantly down-regulated in germinal centre (GC) B-cell-like diffuse large B-cell lymphoma (GCB-DLBCL), which display constitutively high BCL6 expression." (PMID 27764808, 2016). "In 4/10 patients with a BCL6+ primary cutaneous diffuse large B-cell lymphoma, leg type (PCDLBCL,LT) and in 2/2 patients with a secondary cutaneous BCL6+ diffuse large B-cell lymphoma (DLBCL), TOX was expressed by more than 50 % of the neoplastic B-cells." (PMID 27180090, 2016). "BCL6 is involved in chromosomal translocations in ∼25% of all cases of diffuse large B-cell lymphoma (DLBCL) and is, therefore, likely to have a major role in driving lymphomagenesis." (PMID 24595451, 2014). "A peptide inhibitor based on the BCL-6 interaction peptide from SMRT has been shown to be effective against diffuse large B-cell lymphoma (DLBCL) in vitro and in mice models." (PMID 21925568, 2012). "Histology showed diffuse large B‐cell lymphoma, germinal center B‐cell type, with co‐expression of CD10, BCL6, and IRF4/MUM1." (PMID 41755940, 2026). "Since MEF2B is a known regulator of BCL6 in normal GC B-cells, diffuse large B-cell lymphoma, and follicular lymphoma, we subsequently focused on the effect of MEF2B knockdown on BCL6." (PMID 41992423, 2026). "Diffuse large B‐cell lymphoma typically expresses pan‐B markers CD19, CD20, CD22, CD79a, CD45RA, PAX5 markers, and other markers CD10, BCL6, BCL2, MYC, and MUM‐1." (PMID 40735721, 2025). "Histopathology confirmed diffuse large B-cell lymphoma of the germinal centre B-cell-like (GCB) subtype (CD20, CD10, BCL6, and MUM1 positive), consistent with IELSG score 2 disease." (PMID 41280952, 2025). "Fourteen years after initial diagnosis, she developed CNS symptoms with cerebellar lesions; resection revealed transformed diffuse large B-cell lymphoma (DLBCL) of germinal center origin (CD5+, CD10+, BCL2, BCL6, MYC+, Ki-67 ~70%)." (PMID 41146768, 2025). "A 52-year-old woman was diagnosed with primary mediastinal of differentiation CD20 (+), CD79a (+), Bcl-2 (+), Bcl-6 (partial+), MUM1 (partial+) diffuse large B cell lymphoma (DLBCL) almost six months prior." (PMID 38561816, 2024). "The fact that BCL6 and EZH2 cooperate to repress transcription leads to concurrent inhibition of EZH2 and BCL6 in diffuse large B cell lymphoma." (PMID 36377663, 2022). "Thus, PRMT5 inhibition derepresses BCL6 target genes, and suppresses DLBCL (diffuse large B-cell lymphoma) proliferation." (PMID 32743345, 2020). "BCL6 (B cell lymphoma-6, also known as ZBTB27), was first identified as an oncogene frequently translocated/hypermutated in diffuse large B cell lymphoma (DLBCL) and follicular lymphoma (FL) cells." (PMID 29616049, 2018). "HSP90aa1 is upregulated in diffuse large B cell lymphoma (DLBCL), along with the key oncoprotein and transcriptional repressor BCL6." (PMID 29216518, 2018). "A similar effect has been demonstrated in multiple diffuse large B-cell lymphoma cell lines, where knockdown of MEF2B led to down-regulation of BCL6 expression and repression of cell growth." (PMID 30514247, 2018).
diffuse large B-cell lymphoma (continued). "In the pathogenesis of Diffuse large B-cell lymphoma (DLBCL), BCL6 transcriptional repressor is the most frequently involved oncoprotein, which is required to sustain proliferation and survival of DLBCL cells through regulation of specific targets such as PRDM1, c-Myc or PAX-5." (PMID 30143009, 2018). "Double expression of MYC and BCL2 proteins (DE) and double-hit MYC+BCL2/BCL6 translocations (DH) were established as important biomarkers in patients with diffuse large B-cell lymphoma (DLBCL) by the 2016 revision of the World Health Organization classification of lymphoid neoplasms." (PMID 29088292, 2017). "In other human malignancies, such as Diffuse Large B Cell Lymphomas (DLBCL), the tumor suppressor function of PATZ1 is proapoptotic, achieved by inhibiting and enhancing transcription of BCL6 and BAX, respectively." (PMID 29186807, 2017). "Double-hit B cell lymphoma (DHL) is defined as diffuse large B cell lymphoma with translocations and/or extra signals involving MYC along with BCL2 and/or BCL6 as identified by FISH." (PMID 25918657, 2015). "In some diffuse large B-cell lymphomas (DLBCL), BCL6 protein expression was positively correlated with the mRNA level of Yin Yang 1 (YY1)." (PMID 25245533, 2014). "LMO2, MYBL1, BCL6, LRMP, and CCND2 in our 35 signature genes were also reported in Lossos's 36 genes, which predicted survival in diffuse large-B-cell lymphoma." (PMID 20856936, 2010). "Diffuse large B cell lymphomas with activated germinal centre B cell (GCB) pattern (CD10+/-, BCL-6+/-, MUM+/-, CD138+/-) had better survival (98.4 months; 95% CI 89.5 -107.3) than the others (57.3 months; 95% CI 35.5 - 79.0) p = 0.027 (log rank test)." (PMID 20003543, 2009). "Diffuse large B-cell lymphoma was most commonly positive for CD20 and CD79a and less commonly positive for germinal centre cell markers CD10 and BCL6." (PMID 19116013, 2008). "Notably, AID facilitates TET2-mediated demethylation of the FANCA gene as a transcriptional cofactor in diffuse large B-cell lymphoma (DLBCL), while paradoxically collaborating with DNMT1 to maintain methylation at the BCL6 promoter." (PMID 40270606, 2025). "CKD-581 treatment also up-regulated the phosphorylation of histone H2AX (γH2AX, DNA double-strand break marker), and reduced levels of MYC and anti-apoptotic proteins such as BCL-2, BCL-6, BCL-XL, and MCL-1 in DH/DE-diffuse large B cell lymphoma (DLBCL) cell lines." (PMID 32575557, 2020). "The diffuse large B cell lymphoma (DLBCL) cell line U-2932 is an example of a cell line comprising subclones, with differential expression of > 100 genes, including the germinal center oncogenes BCL6 and MYC." (PMID 27566572, 2016). "It was shown that the C-terminal domain of BCL-6 physically interacts with the Rel-homology domain of NF-κB in vitro as with AP1 family members and that BCL-6 behaves as a mutual negative regulator of NF-κB target genes in diffuse large B-cell lymphomas." (PMID 26162096, 2015). "A para-aortic LN biopsy revealed transformation to diffuse large B-cell lymphoma (DLBCL) with CD10 +, ki-67 proliferation index >90%, C-MYC >50%, FISH showing BCL2+, BCL6+, and MYC +." (PMID 41306534, 2025). "Biopsy confirmed diffuse large B-cell lymphoma (DLBCL), with immunohistochemistry positive for CD45, CD20, and BCL6." (PMID 39610570, 2024). "The histopathology showed tumour cells positive for CD20 and BCL6 with an MIB1 proliferative index of 95%, consistent with a diagnosis of high-grade diffuse large B-cell lymphoma (DLBCL) of the germinal center type." (PMID 39650938, 2024).